SHH (sonic hedgehog signaling molecule)
Diseases named in the same sentence as SHH in open-access papers (continued):
Sharing a sentence is not in itself a finding about the gene and the disease.
medulloblastoma (continued). "For instance, NKX2-2AS has been shown to suppress tumorigenesis in SHH-driven medulloblastoma, while HHIP-AS1, TP73-AS1, CCAT1, CRNDE, LOXL1-AS1, ANRIL, and linc-NeD125 have been reported to promote medulloblastoma cell proliferation and migration." (PMID 37976029, 2023). "PRMT5 also represents a requisite driver of tumor progression in SHH-medulloblastoma and MYC-amplified medulloblastoma." (PMID 38136401, 2023). "Of these seven genes (LTBP1, MAP1A, MBNL2, LGALS1, PNRC1, DAB2, and PLAAT3), only one, LGALS1, had been researched previously in relation to medulloblastoma, where it is up-regulated in MBSHH patients and activated by the SHH signalling pathway." (PMID 36831428, 2023). "As SHH signaling drives CGNP proliferation and medulloblastoma tumorigenesis, PRC2-mediated repression of SHH target genes suggests the potential to inhibit proliferation in SHH-driven cells." (PMID 36635771, 2023). "Medulloblastomas have also been categorized into four molecular subtypes: WNT, SHH, Group 3, and Group 4, according to the clinical and genetic features." (PMID 37335442, 2023). "As expected, overexpression of SHH itself significantly increased proliferation, and overexpression of GNAS, which has been identified as a tumor suppressor gene in the SHH subtype of medulloblastoma, significantly inhibited proliferation." (PMID 36995257, 2023). "Most (n = 95) embryonal tumors were medulloblastomas from four characterized molecular subtypes (WNT, SHH, group 3, and group 4; see molecular subtyping of OpenPBTA CNS tumors), as identified by subtype-specific canonical mutations." (PMID 37492101, 2023). "The in silico analysis of medulloblastomas from the North American and European (NAM/EU) populations showed that 29% (n=176) was SHH activated, 39% (n=240) Group 4, 24% (n=148) Group 3, and 8% (n=53) WNT activated." (PMID 37746264, 2023). "Finally, considering that CAL SHH ATRT and infant SHH medulloblastomas develop in the cerebellum of young children and activate the SHH pathway, we assumed that a comparison of gene expression of these two types of tumors could also be relevant on the actual identity of CAL SHH ATRT." (PMID 37863903, 2023). "Initially, medulloblastoma was classified as being WNT-activated, SHH-activated, group 3 and group 4." (PMID 37509034, 2023). "Molecular profiling has revealed four molecular subgroups of medulloblastoma—wingless (WNT), sonic hedgehog (SHH), Group 3, and Group 4—with distinct molecular and clinical profiles." (PMID 36303547, 2022). "Medulloblastoma is a classical developmental cancer and is commonly believed to originate from cerebellar granule progenitors (CGP) that normally depend on SHH signaling for proliferation." (PMID 36688010, 2022). "Using the stringent cutoffs of padj < 0.05 and |log2FoldChange| > 1, circular RNAs differentially expressed in the SHH, WNT, Group 3 and Group 4 medulloblastoma subtypes compared to cerebellum were identified." (PMID 35804907, 2022). "Medulloblastoma (MB) is one of the most common childhood malignant brain tumors (WHO grade IV), traditionally divided into WNT, SHH, Group 3, and Group 4 subgroups based on the transcription profiles, somatic DNA alterations, and clinical outcomes." (PMID 35273141, 2022).
medulloblastoma (continued). "Using both spontaneous and transplantable mouse models of sonic hedgehog (SHH) medulloblastoma treated with a SHH/Smoothened inhibitor (SMOi), sonidegib/LDE225, we show that genetic-based resistance occurs only in tumors that contain SHH-dependent CSCs." (PMID 36688010, 2022). "Using stringent statistical criteria, 367, 185, 188 and 210 circular RNAs de-regulated in the SHH, WNT, Group 3 and Group 4 subtypes of medulloblastoma, respectively, in comparison to cerebellum, were identified." (PMID 35804907, 2022). "According to this classification, there are four genetic (molecular) groups of medulloblastoma: the wingless (WNT)-activated and the Sonic Hedgehog (SHH)-activated groups, and the groups numerically designated as “group 3” and “group 4”." (PMID 33822292, 2021). "For medulloblastomas, molecular categories also correspond to different prognoses, which vary from good (WNT-activated) to intermediate (SHH-activated and group 4) to poor (group 3)." (PMID 33498680, 2021). "Another example is the miR-17/92 cluster overexpression that is related to activated SHH/PTCH pathways and influences medulloblastoma growth." (PMID 34066495, 2021). "Transcriptomic studies have identified four major subgroups of medulloblastoma: WNT, SHH, group 3, and group 41." (PMID 34021242, 2021). "The requirement of ATOH1 for the formation of SHH-activated medulloblastoma is mediated by direct binding of ATOH1 to the SHH pathway effector, GLI2, which maintains GCPs in a SHH-responsive state." (PMID 34012965, 2021). "Some of them affect miRNA activity (miRNA sponging) and pathways of medulloblastoma development (MAPK, SHH, PI3K/AKT)." (PMID 34066495, 2021). "A more recent classification, based on genomics data, also divides medulloblastomas into four subgroups known as Wingless (WNT) and Sonic Hedgehog (SHH), which are better described and Group 3 (Grp3) and Group 4 (Grp4) less characterized." (PMID 34944941, 2021). "In medulloblastoma, YAP1 is significantly amplified and upregulated in SHH-activated subtypes and mediates SHH-driven NPC proliferation." (PMID 34012965, 2021). "These PC are essential for the regulation of several signaling pathways, such as SHH and WNT, and they can promote tumorigenesis in medulloblastoma." (PMID 34436033, 2021). "A systemic review and metanalysis on five clinical phase 1/2 trials exploring the efficacy of anti-SHH agents vismodegib and sonidegib showed that the pooled objective response rate (ORR) of SHH-inhibitors was 37% in SHH-driven medulloblastomas." (PMID 34360713, 2021). "These genes have not (yet) been implemented in routine genetic testing strategies for patients with the suspected diagnosis of Gorlin syndrome and might (partially) close the diagnostic gap in young children with SHH-activated medulloblastomas lacking germline PTCH1 or SUFU mutations." (PMID 34888241, 2021). "Both proteins of DLL1 and NCAM1 are detected in medulloblastoma tissues of patients in four subgroups: WNT, SHH, group 3 and group 4." (PMID 34857809, 2021). "Extensive transcriptomic analyses have categorized medulloblastoma into four molecular subgroups: WNT, SHH, Group 3, and Group 4, that can be further stratified into 13 molecular subtypes." (PMID 33477420, 2021). "Medulloblastomas can be divided into WNT, sonic hedgehog (SHH), Group 3, and Group 4 molecular subgroups." (PMID 33425720, 2020). "Medulloblastomas are now classified into four major molecular groups (WNT-activated, SHH-activated, Group 3, and Group 4) with distinct clinical, genetic and transcriptomic profiles." (PMID 33172502, 2020).
medulloblastoma (continued). "With increasing accessibility to advanced molecular genetic techniques, medulloblastoma has been further classified based on its distinct molecular subtypes (WNT, SHH, Group 3, and Group 4), shedding new light on potential therapeutic targets." (PMID 32903405, 2020). "Activation of the canonical WNT and SHH signaling pathway is a characteristic of the WNT, and SHH subgroup medulloblastomas, respectively." (PMID 32410663, 2020). "Medulloblastoma, a common type of malignant brain cancer that accounts for 8-10% of childhood brain tumors, comprises four molecular subgroups (WNT, SHH, group 3, group 4) that have differing prognoses." (PMID 33323540, 2020). "The 2016 WHO Classification presents a restructuring of medulloblastomas and other embryonal tumors, medulloblastomas, WNT-activated, medulloblastomas, SHH-activated, and embryonal tumors with multilayered rosettes, C19MC-altered." (PMID 32325928, 2020). "It is established that medulloblastoma can be characterized into at least four major subgroups, Wingless (WNT), Sonic hedgehog (SHH), group 3, and group 4." (PMID 32508873, 2020). "They subsequently performed immunohistochemistry for GAB1, which yielded a focal staining pattern that confirmed secondary SHH pathway activation, reflecting intratumoural heterogeneity within these WNT medulloblastomas." (PMID 33172502, 2020). "Current molecular classification divides medulloblastomas into at least four molecular subgroups: WNT, Sonic Hedgehog (SHH), Group 3 and Group 4, initially defined based on expression microarrays and reflecting their different biology." (PMID 31554835, 2019). "Recently, medulloblastoma have been classified into four subgroups: WNT, SHH, Group 3 and Group 4 that differ in their ontogeny, demographics and clinical outcomes." (PMID 30657775, 2019). "Brd4 controls expression of the medulloblastoma essential gene MYC in G3 medulloblastomas, which have poor prognosis as well as GLI1 and GLI2 levels in Sonic hedgehog (SHH)-driven medulloblastomas, which have intermediate prognosis." (PMID 31292434, 2019). "Recent advances in cancer genetics and genomics have classified medulloblastoma into four molecular subgroups: WNT, SHH, group 3 (c-Myc overexpression), and group 4." (PMID 31788346, 2019). "The frequency of medulloblastoma patients in these four groups were 34% for GPR4, 28% for SHH, 27% for GPR3, and 11% for WNT." (PMID 30279357, 2018). "Vismodegib, a SHH pathway inhibitor that binds SMO, was tested in pediatric and adult recurrent medulloblastomas, showing antitumor activity only in the SHH-subgroup of medulloblastomas." (PMID 30279357, 2018). "We investigated the role of AMPKα2 in vivo in medulloblastoma using the [GFAP-tTA;TRE-SmoA1] genetically engineered mouse model of SHH-driven medulloblastoma in combination with the AMPKα2 KO mouse." (PMID 30360486, 2018). "In 2012 a general consensus was reached regarding the existence of only four molecular subgroups of medulloblastomas, termed WNT, SHH, Group 3 (GPR3), and Group 4 (GPR4)." (PMID 30279357, 2018). "Medulloblastoma is characterized by four major molecularly and histopathologically distinct groups, wingless (WNT), sonic hedgehog (SHH), group 3 (G3), and group 4 (G4), that, except for WNT, are each now subdivided in several subgroups." (PMID 29178021, 2018). "First, in medulloblastoma cells, AMPK phosphorylates the SHH pathway transcription factor GLI1, promoting its proteasomal degradation, thus inhibiting SHH signaling and SHH-driven medulloblastoma." (PMID 30360486, 2018). "While all studies in which the role of AMPK has been directly tested genetically in human medulloblastoma cells agree, i.e., AMPK suppresses SHH-driven cell growth, the role of AMPK in mouse cell lines is debated." (PMID 30360486, 2018). "Genomics applied to medulloblastoma defined four medulloblastoma subgroups (WNT, SHH, and Groups #3 and #4) and, more recently, different subtypes within them." (PMID 30360486, 2018).
medulloblastoma (continued). "Human medulloblastoma is divided in at least 4 molecular subgroups (WNT, SHH, Group 3, and Group 4) which are characterized by different patterns of gene expression, genetic aberrations, and clinical outcomes." (PMID 30443541, 2018). "After uncovering a potential role for the HDL receptor, SCARB1, in SHH-driven medulloblastoma, we tested the effect of synthetic HDL NPs on SHH-driven cancer cells." (PMID 29352211, 2018). "In addition to attempting to inhibit SHH signaling—a strategy that can be foiled by the development of secondary mutations —we hypothesized that controlling the levels of Atoh1 protein will provide another therapeutic entry point for the treatment SHH-driven medulloblastoma." (PMID 29168692, 2017). "Medulloblastomas comprise a heterogeneous group of tumours and can be subdivided into four molecular subgroups (WNT, SHH, Group 3 and Group 4) with distinct prognosis, biological behaviour and implications for targeted therapies." (PMID 28417956, 2017). "We first identified a DNA methylation signature of 17 CpG loci, established detection methods and developed a Support Vector Machine (SVM) classification model for distinction of the four medulloblastoma molecular subgroups (WNT, SHH, Grp3 and Grp4)." (PMID 29044166, 2017). "Medulloblastoma comprises four main subgroups (WNT, SHH, Group 3 and Group 4) originally defined by transcriptional profiling." (PMID 28231263, 2017). "Transcriptional and epigenetic profiling has described how medulloblastomas can be divided into four molecular subgroups (WNT, SHH, Group 3 and Group 4) with distinct demographics, clinical outcome and implications for targeted therapies." (PMID 28417956, 2017). "Medulloblastoma comprises four primary molecular subgroups – WNT, SHH, Grp3 and Grp4 - defined by distinct methylomic, transcriptomic and genomic features." (PMID 29044166, 2017). "The GTML model gives rise to tumors that mostly (>80%) resemble Group 3 medulloblastoma but also smaller sets of WNT, SHH, and Group 4 tumors accentuating MYCN as a pleiotropic transcription factor in medulloblastoma tumorigenesis." (PMID 28333115, 2017). "International consensus recognises four medulloblastoma molecular subgroups: WNT (MBWNT), SHH (MBSHH), group 3 (MBGrp3), and group 4 (MBGrp4), each defined by their characteristic genome-wide transcriptomic and DNA methylomic profiles." (PMID 28545823, 2017). "In adult patients, only three biological medulloblastoma subgroups have been identified: WNT, SHH, and group 4." (PMID 27781424, 2016). "In contrast, CD15+ TPCs are resistant to cisplatinum, temozolomide and the SHH inhibitor, NVP-LDE-225, agents currently used in treatment of medulloblastoma." (PMID 26938241, 2016). "Transcriptome analysis of human medulloblastomas shows that SERPINE2, also called Protease Nexin-1 (PN-1) is overexpressed in most medulloblastomas, in particular in the SHH and WNT subgroups." (PMID 25901736, 2015). "SERPINE2/PN-1 is expressed in most human medulloblastomas, with levels being highest in the two subgroups with altered WNT and SHH pathway activities." (PMID 25901736, 2015). "Our initial comparative analysis of the transcriptomes of human medulloblastomas and other brain tumors showed that SERPINE2/PN-1 is expressed at high levels in the WNT and SHH subgroups." (PMID 25901736, 2015). "Medulloblastoma has been recognized to be a heterogeneous disease, and no recurrent cancer gene mutations have been found, although many of the mutations described so far affect key intracellular signaling pathways, such as sonic hedgehog (SHH) and Wnt/β-catenin." (PMID 25915540, 2015). "This motivates to investigate the interplay between the SHH and EGFR dependent pathways in a presumable medulloblastoma model system from a computational point of view." (PMID 26571415, 2015). "This motivates to computationally model the interactions between SHH and EGFR dependent pathways in Daoy cells as a presumable model system for medulloblastoma." (PMID 26571415, 2015).
medulloblastoma (continued). "Based on transcriptomic approaches the current consensus is that medulloblastoma is comprised of four distinct molecular subgroups - SHH, WNT, group 3 and group 4 – which correspond in part to the former histological WHO classes for medulloblastoma." (PMID 25216529, 2014). "To answer this question, we analyzed two publicly accessible sets of gene expression data on human medulloblastomas, which had been assigned to one of four molecular subgroups (WNT, SHH, Group 3, and Group 4)." (PMID 25059231, 2014). "Current consensus identifies four molecular subtypes of medulloblastoma (MB): WNT, sonic hedgehog (SHH), and groups “3/C” and “4/D”." (PMID 25030029, 2014). "The four molecular subgroups of medulloblastoma that have been identified – WNT, SHH, Group 3 and Group 4 - have molecular and topographical characteristics suggestive of different cells of origin." (PMID 25412507, 2014). "Distinct GPCRs are uniquely over-expressed in the WNT and SHH subgroups, as well as in three other groups of tumors, strongly suggesting that GPCR targets specific to each medulloblastoma subgroup can be identified." (PMID 24252460, 2013). "Medulloblastoma (MB) is a malignant pediatric brain tumor arising in the cerebellum consisting of four distinct subgroups: WNT, SHH, Group 3 and Group 4, which exhibit different molecular phenotypes." (PMID 23567267, 2013). "Inhibition of SHH-GLI signalling pathway in BCC and medulloblastoma using specific inhibitors is accompanied by a significant clinical response." (PMID 23935925, 2013). "Group 4 medulloblastomas have a higher proportion of seeding at presentation than WNT and SHH subgroups, but MYC amplification and anaplasia are seldom found in the subgroup." (PMID 23768125, 2013). "Also, the interactions between MYCN and the SHH signaling raises the possibility of combined SHH/MYCN-targeted therapies, similar to those used in SHH-subgroup medulloblastomas." (PMID 40365336, 2025). "This pattern was associated with reduced ZIC1/ZIC4 transcript levels and was not recurrently observed in either SHH or WNT medulloblastoma." (PMID 39753768, 2025). "Molecular analyses classify medulloblastoma into the WNT, SHH, Group 3 and Group 4 subgroups." (PMID 40148468, 2025). "Sonic hedgehog (SHH) medulloblastoma is the most common molecular group of infant and early childhood medulloblastoma (iMB) and has no standard of care at relapse." (PMID 40186336, 2025). "Understanding the mechanism(s) by which AMPK inhibition halts medulloblastoma cell proliferation and survival may allow the design of potential targeted therapies that exploit the role of AMPK in SHH-driven medulloblastoma and other cancers." (PMID 39779613, 2025). "Among those tumors, medulloblastoma is grouped into four distinct molecular subgroups in terms of gene expression patterns, one of which is SHH group, in which the amplifications of MYCN and MYCL are most frequently observed, defining its pathological significance in medulloblastoma." (PMID 38884091, 2024). "Medulloblastoma is a heterogeneous disease comprising four broad molecular subgroups (WNT, SHH, Group 3, and Group 4) with subgroup-specific developmental origins, unique genetic profiles, distinct clinico-demographic characteristics, and varying clinical outcomes." (PMID 38396397, 2024). "Medulloblastoma (MB) comprises four broad molecular subgroups, namely wingless (WNT), sonic hedgehog (SHH), Group 3, and Group 4, respectively, with subgroup-specific developmental origins, unique genetic profiles, distinct clinico-demographic characteristics, and diverse clinical outcomes." (PMID 38396397, 2024).